FOXP3 (forkhead box P3)
Diseases named in the same sentence as FOXP3 in open-access papers (continued):
Sharing a sentence is not in itself a finding about the gene and the disease.
experimental autoimmune encephalomyelitis (continued). "A recent study using experimental autoimmune encephalomyelitis (EAE) reported that lack of T-bet expression in Foxp3+ Tregs did not hinder their infiltration of the inflamed central nervous system, which is important for EAE resolution." (PMID 26433463, 2015). "However, in the experimental autoimmune encephalomyelitis (EAE) model, apitope-induced tolerance was also mediated by IL-10 producing Foxp3-negative Tr1 cells, similar to what we think our mCTA1–T146 fusion protein does in the EAMG model." (PMID 28959261, 2017).
Stroke (36 papers, 2011 to 2026). Sudden impairment of blood flow to a part of the brain due to occlusion or rupture of an artery to the brain. "Studies on immune responses following stroke have revealed that CD4+CD25+Foxp3+ regulatory T cells play crucial and complex roles in controlling the inflammatory damage caused by stroke as well as modulating immunosuppression." (PMID 36582228, 2022). "Our study shows that Qi deficiency and blood stasis of CHD and stroke includes some inflammatory factors: IL-10, FOXP3, cell apoptosis, differentiation, and proliferation." (PMID 32670064, 2020). "The present study unveiled the existence of an immunopathological outcome underlying chagasic patients condition that involves an imbalanced expression of IL-10, FoxP3 and iNOS, which increases the risk of stroke or death." (PMID 27115869, 2016). "Therefore, future investigations should focus on the reliable definition as well as the further determination of the real roles and underlying mechanisms of FoxP3+CD25+CD4+ Treg-mediated immune regulation following stroke." (PMID 23983771, 2013). "Flow cytometry analysis showed that compared with the MCAO + IgG group, the ratio of CD4+CD25+Foxp3+ Tregs increased significantly in the MCAO + IL‐2:IL‐2 Ab group on the 14th day after stroke." (PMID 41552852, 2026). "A previous study demonstrated that FOXP3+ macrophages are beneficial for stroke outcomes by inhibiting IS-induced neural inflammation." (PMID 40264650, 2025). "Case Control Study seeking to determine by peripheral blood samples if patients that experience an increase in anti inflammatory Treg cells (CD4+, CD25, +FoxP3+, “brain” Treg) after stroke have improved clinical outcomes. // Recruiting." (PMID 40356948, 2025). "Individuals with chronic Chagas cardiomyopathy at low stroke risk show increased expression of GATA-3, Foxp-3, and IL-1034." (PMID 39907396, 2025). "Electroacupuncture has been proved to increase the levels of SCFA, a metabolite of gut microbiota in an ischemic stroke rat model, and attenuate brain and gut inflammatory injury in stroke rats by enhancing SCFA-mediated Foxp3 acetylation in Treg cells." (PMID 40098933, 2025). "Given the protective effects of Tregs in post-stroke outcomes in other studies, we performed immunostaining for Foxp3, a specific nuclear marker for Tregs." (PMID 36533127, 2022). "We found for the first time that NBP significantly increased Foxp3 expression in the ischemic area in an animal stroke model." (PMID 33461169, 2021). "Total FoxP3+ Tregs and CD39+FoxP3+ Tregs were quantified by flow cytometry in controls and stroke patients on admission and on days 1, 3, 5, and 7 thereafter." (PMID 27073295, 2016). "We observed that low stroke risk patients exhibited higher GATA-3, Foxp3, PU.1, AHR, IL-9, IL-10 and IL-22 expression levels than did patients with high stroke risk." (PMID 27115869, 2016). "In this study, we demonstrated that patients with low stroke risk have increased mRNA expression of GATA-3, Foxp3, PU.1, AHR, IL-9, IL-22 and IL-10." (PMID 27115869, 2016). "FOXP3 mRNA was significantly decreased in patients at 7 and 28 days after stroke compared with controls." (PMID 24991091, 2014). "Although many review articles have focused on FoxP3+CD25+CD4+ Tregs, a new review is necessary for appraising recent research advances in FoxP3+CD25+CD4+ Tregs after stroke." (PMID 23983771, 2013). "Secondly, the fundamental questions regarding FoxP3+CD25+CD4+ Tregs, such as their temporal and spatial dynamics, significance, and underlying immunomodulatory mechanisms in stroke, need to be answered." (PMID 23983771, 2013). "Specifically, FoxP3+CD25+CD4+ Tregs exert neuroprotective effects in acute experimental stroke models." (PMID 23983771, 2013). "FoxP3+CD4+ Tregs appear to exert an unfavorable role as immunosuppressive modulators and increase infection susceptibility following stroke." (PMID 23983771, 2013).
Stroke (continued). "Identification of the poststroke temporal and spatial distribution of FoxP3+CD25+CD4+ Tregs has assisted in elucidating their roles in stroke." (PMID 23983771, 2013). "In conclusion, both beneficial and detrimental effects of FoxP3+CD25+CD4+ Tregs in stroke have been currently referenced." (PMID 23983771, 2013). "It is imperative to advance our understanding and authenticate the roles of FoxP3+CD25+CD4+ Tregs and their underlying mechanisms in stroke pathophysiology." (PMID 23983771, 2013). "Particularly, studies reported that FoxP3+CD25+CD4+ Tregs are important neuroprotective immunomodulators in stroke, but their contributive effects towards stroke pathophysiology are still controversial." (PMID 23983771, 2013). "Altogether, the temporal and spatial dynamics of FoxP3+CD25+CD4+ Tregs after stroke are still controversial." (PMID 23983771, 2013). "Our understanding of FoxP3+CD25+CD4+ Tregs in stroke has advanced considerably, based on the following key findings." (PMID 23983771, 2013). "Peter Kraft from Christoph Kleinschnitz`s group in Würzburg investigated the role of Foxp3 positive regulatory T cells (Treg) in experimental stroke using DEREG mice." (PMID 23174128, 2012). "Furthermore, this chemokine also induces FoxP3+ regulatory T (Treg) cell migration into the brain, where they take part in neurological recovery after stroke, mostly by reducing astrogliosis." (PMID 37765263, 2023). "Sadler et al16 also found that the increase of intestinal segmented filamentous bacteria after stroke can affect the differentiation of T lymphocytes, which reduced the Foxp3/IL‐17 ratio in intestinal lymphoid tissue and expanded pro‐inflammatory Thl7 cell, thus aggravating ischemic brain injury." (PMID 37309276, 2023). "The role of CD4+Foxp3+ Treg cells in stroke recovery, however, remains divergent in might be dependent on the stroke model, different microenvironments in the post-ischemic brain as well as the time intervals after the insult." (PMID 35401118, 2022). "PSGs may also be strong promoters of a subpopulation of CD25+ Foxp3+ T cells termed regulatory T cells (or “Tregs”), a cell type well-characterised as contributing to post-stroke repair." (PMID 36120102, 2022). "However, Foxp3 expression was slightly higher after stroke in 1,25-VitD3-treated mice than in sham mice or in those treated with vehicle." (PMID 29476479, 2018). "Moreover, we noted an increase in the T regulatory cell transcription factor, Foxp3, after stroke, and this was augmented in 1,25-VitD3-supplemented animals." (PMID 29476479, 2018). "A negative correlation was observed between Foxp3 and death risk (r = -0.4983; p = 0.0051) and stroke risk (r = -0.5359; p < 0.0001)." (PMID 27115869, 2016). "Previous studies reported an increase in FoxP3 expression and in Treg-cell numbers in the spleen and blood following experimental ischaemia and differences in Treg-cell numbers in the blood from patients 7 days after a stroke." (PMID 24889329, 2014). "Moreover, another study declared that FoxP3+CD4+ Tregs greatly augmented acute ischemic/reperfusion injury after stroke, and this detrimental effect persisted into the later period of infarct development in a DEREG mouse model." (PMID 23983771, 2013). "Therefore, the principle issue behind a therapeutic intervention based on FoxP3+CD25+CD4+ Treg modulation is identifying the precise roles of FoxP3+CD25+CD4+ Tregs at specific stages of stroke." (PMID 23983771, 2013). "Some evidence depicts the unique role of FoxP3+CD25+CD4+ Tregs in stroke pathogenesis." (PMID 23983771, 2013). "The increased presence of FoxP3+CD4+ Tregs might participate in stroke-induced immunosuppression on the peripheral immune system." (PMID 23983771, 2013). "The lack of a substantial number of severe stroke patients in this study, however, may deceptively lead to overlooking the effects of stroke severity on the number of FoxP3+CD25+CD4+ Tregs." (PMID 23983771, 2013).
Stroke (continued). "CD4+CD25+FoxP3+ naturally occurring regulatory T cells have been shown to reduce the impact of stroke and may have similar protective roles in the injured brain." (PMID 22152221, 2011). "As seen for IL-37, several other anti-inflammatory markers, namely Foxp3 (P = 0.012), Ym1 (P = 0.006), Il-10 (P = 0.018), Il-13 (P = 0.002) and Tgfb (P = 0.008) were up to 3-fold increased in the ischemic hemisphere following stroke in IL-37tg compared to WT mice." (PMID 31061403, 2019). "Importantly, FoxP3+CD25+CD4+ Treg-mediated immunosuppression could be protective or harmful at different stages of stroke." (PMID 23983771, 2013). "In addition, significant differences between male and female stroke patients in the frequency and suppressive effects of FoxP3+CD25+CD4+ Tregs were demonstrated in this study, but the underlying reasons for these observed differences are unknown." (PMID 23983771, 2013). "Whether FoxP3+CD25+CD4+ Tregs are friends or foes in stroke, however, remains unclear." (PMID 23983771, 2013). "Moreover, because evidence acquired from animal experiments is often difficult to transfer into clinical study, more attention should be paid to the translational value between basic research and clinical trials in the investigation of FoxP3+CD25+CD4+ Tregs following stroke." (PMID 23983771, 2013). "For example, Foxp3‐plasmid‐loaded PLGA NPs (100–150 nm) delivered Foxp3 to microglia and significantly reduced inflammatory cytokines (e.g., TNF, IL-1β, IL-6, iNOS) in stroke models." (PMID 41583439, 2025). "Notably, reduced expression of transcription factors (GATA-3, FoxP3), cytokine IL-10, and elevated mRNA expression of IFN-γ, TNF-α, and inducible nitric oxide synthase (iNOS) have been observed to increase the risk of death from stroke in these patients patients." (PMID 39217407, 2024). "A previous report described staining for Foxp3 in the striatal and cortical regions of the brain after ischemia and reperfusion in an MCAO-induced stroke model." (PMID 33461169, 2021). "Subsequently, we analyzed the correlation between the mRNA expression of Foxp3, IL-10, TNF-α and iNOS with the death and stroke risks." (PMID 27115869, 2016). "More studies are required to further clarify the distribution of FoxP3+CD25+CD4+ Tregs in the CNS, peripheral blood, and lymphatic organs at different phases following stroke." (PMID 23983771, 2013). "FoxP3+CD25+CD4+ Tregs are involved in a variety of central nervous system diseases and injuries, including axonal injury, neurodegenerative diseases, and stroke." (PMID 23983771, 2013). "In a prospective cohort, CD4 + FoxP3+ cells and not CD4 + CD25 + FoxP3+ cells were independent predictors of acute myocardial infarction whereas no relation was found with stroke." (PMID 26822994, 2016). "Like in PBMC, in the ratios of CD4+/CD8+ T cells and Foxp3+/Foxp3− in CD4+ cells were not changed in the spleen in WT rats after stroke." (PMID 23555048, 2013). "One study demonstrated that depletion of FoxP3+CD4+ Tregs by utilizing diphtheria toxin prior to stroke induction failed to reduce infarct volume at 96 hours after MCAO and reperfusion injury." (PMID 23983771, 2013). "Recently, several findings do not support the neuroprotective effects of FoxP3+CD25+CD4+ Tregs in stroke treatment." (PMID 23983771, 2013). "While FoxP3+CD25+CD4+ Tregs have beneficial effects after stroke, we should not ignore their possible detrimental effects." (PMID 23983771, 2013). "The ratios of CD4+/CD8+ and Foxp3+/Foxp3− in CD4+ cells were not altered in stroke animals compared with naïve and sham surgery rats." (PMID 23555048, 2013). "Specifically, FoxP3+CD25+CD4+ Tregs acquired notable attention because of their role in a variety of central nervous system (CNS) and autoimmune pathologies, such as multiple sclerosis (MS), stroke, and glioblastomas." (PMID 23983771, 2013).
Stroke (continued). "The frequency of CD4+ Foxp3+ regulatory cells in the spleen increases after MCAO although there are contradicting data on whether CD4+ regulatory T cells diminish or exacerbate stroke related neuronal damage." (PMID 25309326, 2014). "Advancing our understanding of FoxP3+CD25+CD4+ Tregs and utilizing FoxP3+CD25+CD4+ Tregs to selectively suppress the deleterious effects of excessive brain immunoreaction after stroke may provide novel therapeutic approaches for stroke patients." (PMID 23983771, 2013). "The results showed that low levels of CD4+FoxP3+ Treg cells but not CD4+CD25+FoxP3+ Treg cells were associated with an increased risk for myocardial infraction, and neither CD4+ FoxP3+ Treg cells nor CD4+CD25+FoxP3+ Treg cells were associated with stroke." (PMID 24385687, 2013). "Considering the absence of other specific strategies or drugs for patients with stroke, modulating the quantity and function of FoxP3+CD25+CD4+ Tregs may be potential, novel avenues for developing new therapeutics that improve neurological outcomes after stroke." (PMID 23983771, 2013). "Furthermore, it has been reported that FoxP3+CD25+CD4+ Tregs may be a facilitator for Cocaine-and-amphetamine-regulated-transcript- (CART-) mediated neuroprotection after stroke." (PMID 23983771, 2013). "Moreover, intravenous albumin administration reduced Toll-like receptor 4 expression but significantly increased FoxP3+CD25+CD4+ Tregs expression levels and elevated IL-10 and TGF-β1 production, eventually conferring neuroprotective effects during postischemic stroke treatment." (PMID 23983771, 2013). "Interestingly, the possibility that endogenous induction of Tregs by BMDCs within the bone marrow cannot be ruled out as a small population (< 0.5%) of CD4+CD25+Foxp3+ Tregs constitute the bone marrow stem cell population which was shown to be neuroprotective in a rat model of experimental stroke." (PMID 29783988, 2018). "The difference seen between our and their results might be due to the fact that different markers were used for the detection of Tregs (in our study, this subset was described as CD4+ CD25high cells, and FoxP3 was not applied) and that the severity of stroke was different in the two investigations." (PMID 24597828, 2014). "Neither stroke nor deletion of Bim affected the number of circulating myeloid cells, neutrophils, Ly6Chi monocytes, CD4+ T cells, or FoxP3+ T cells." (PMID 35149957, 2022).
tuberculosis (34 papers, 2009 to 2025). A chronic, recurrent infection caused by the bacterium Mycobacterium tuberculosis. "An additional investigation reported that the elevation of FOXP3 expression is linked to the polymorphic variant A allele in FOXP3 rs2232365 which potentially leads to an increase in the risk of tuberculosis." (PMID 39117877, 2024). "Our outcome suggests that the −924 A > G polymorphism leads to enhance FoxP3 gene expression and susceptibility to tuberculosis in the sex dependent manner." (PMID 29020928, 2017). "According to our knowledge, our work was the first finding of the assessment polymorphisms A to G in the promoter of FoxP3 gene and its relation to susceptibility to tuberculosis." (PMID 29020928, 2017). "In summary, our outcome suggests that the −924 A > G polymorphism leads to enhance FoxP3 gene expression and susceptibility to tuberculosis in the sex dependent manner." (PMID 29020928, 2017). "Nevertheless, these findings still remain unclear and Larger-scale studies involving multiple centers are needed to elucidate further the role of FoxP3 gene polymorphism in tuberculosis." (PMID 29020928, 2017). "However, little information exists on the relationship between FoxP3 gene polymorphisms and expression with the susceptibility to infectious disease especially tuberculosis." (PMID 29020928, 2017). "According to what was said, we hypothesized two SNP in promoter of FoxP3 gene is related to an increase in FoxP3 gene expression and result in susceptibility to tuberculosis in our target population." (PMID 29020928, 2017). "Recently, FOXP3-positive regulatory T cells (Tregs) have been characterized as one of the most efficient subsets of suppressor effector T cells, which regulate the immune response caused by the host during intracellular infections, such as tuberculosis and leishmaniasis." (PMID 34748560, 2021). "The aim of this study was to evaluate possible associations between two Single nucleotide polymorphisms (SNPs) in the promoter of the FoxP3 gene to susceptibility to tuberculosis (TB) and the alteration of Foxp3 gene expression." (PMID 29020928, 2017). "In a guinea pig model of tuberculosis it was shown that highly virulent strains induce high levels of FoxP3, IL-10, and TGF-β mRNA expression in lung tissue." (PMID 32425944, 2020). "People with active tuberculosis have increased numbers of circulating regulatory CD4 T cells (that express CD25 + FoxP3+) and a greater IFN-γ response, compared to those with latent infection." (PMID 30760258, 2019). "Our findings suggest that tuberculosis pathogenesis results from a failure of CD4+Foxp3+ cell-mediated immune regulation." (PMID 30584243, 2018). "As our previous observation, FoxP3 gene expression in tuberculosis patients was 2.8 fold higher than normal group (CI = 1.29 ± 2.37, P ≤ 0.001)." (PMID 29020928, 2017). "Previous studies have indicated that Foxp3+ Tregs regulate immune responses in the development of tuberculosis and the growth of malignant tumors." (PMID 26283421, 2015). "We noticed a significant inverse relationship of CD4 count with respect to the frequency of Tregs and FoxP3 expression, making these subjects more vulnerable to active tuberculosis in this immune-compromised state." (PMID 25198707, 2014). "Recently we and others have demonstrated that Foxp3+ regulatory T cells are over represented in tuberculosis and suppress the host effector T cell response against Mtb. particularly at the pathologic site of disseminated tuberculosis." (PMID 23028594, 2012). "Our results demonstrated that the diminished IL-4Rα signalling on Foxp3+ T regulatory cells resulted in a loss of their functionality, leading to survival benefits in listeriosis but not in tuberculosis." (PMID 39483462, 2024). "Our results provide insight into the tissue resident Foxp3+ regulatory T cell response during repetitive flu infections, which may be applicable to other respiratory infectious diseases such as tuberculosis and COVID." (PMID 36159872, 2022).